SPOPL (speckle type BTB/POZ protein like)
Description:
Component of a cullin-RING-based BCR (BTB-CUL3-RBX1) E3 ubiquitin-protein ligase complex that mediates the ubiquitination and subsequent proteasomal degradation of target proteins, but with relatively low efficiency. Cullin-RING-based BCR (BTB-CUL3-RBX1) E3 ubiquitin-protein ligase complexes containing homodimeric SPOPL or the heterodimer formed by SPOP and SPOPL are less efficient than ubiquitin ligase complexes containing only SPOP. May function to down-regulate the activity of cullin-RING-based BCR (BTB-CUL3-RBX1) E3 ubiquitin-protein ligase complexes that contain SPOP.
Synonyms: BTBD33
Tractability: PROTAC: ubiquitination databases record sites on it.
Gene: Protein-coding gene on chromosome 2 (138,501,770 to 138,574,458, forward strand). Ensembl gene ENSG00000144228.
Subcellular location: Nucleus
Subcellular location (Human Protein Atlas): Vesicles
Pathways (Reactome):
Signal Transduction: Hedgehog 'on' state
Gene Ontology:
Molecular function: identical protein binding; protein binding; ubiquitin protein ligase binding
Biological process: negative regulation of protein ubiquitination; proteasome-mediated ubiquitin-dependent protein catabolic process; regulation of proteolysis; protein ubiquitination
Cellular component: Cul3-RING ubiquitin ligase complex; cytoplasm; nucleus
Genetic constraint (gnomAD): Loss-of-function variants: 23 observed, 55.71 expected, observed/expected ratio (o/e) 0.41, 90% interval 0.3 to 0.58. The upper end of that interval is the gene's LOEUF score, 0.58, which puts it in group 2 of 6, group 1 being the genes least tolerant of losing a copy. Missense variants: 442 observed, 487.78 expected, observed/expected ratio (o/e) 0.91, 90% interval 0.84 to 0.98. Synonymous variants: 164 observed, 157.02 expected, observed/expected ratio (o/e) 1.04, 90% interval 0.92 to 1.19.
Homologues: Orthologues: chimpanzee SPOPL (100% identical), macaque SPOPL (99% identical), guinea pig SPOPL (99% identical), rabbit SPOPL (99% identical), pig SPOPL (99% identical), mouse Spopl (96% identical), rat Spopl (96% identical), zebrafish spopla (91% identical), dog SPOPL (89% identical), zebrafish spoplb (89% identical), tropical clawed frog spopl (76% identical), Caenorhabditis elegans spop-1 (60% identical). Paralogues in human: SPOP (81% identical), ABTB3 (22% identical), ABTB2 (18% identical), BTBD1 (18% identical), BTBD2 (18% identical), BTBD3 (18% identical), BTBD6 (16% identical), BTBD9 (13% identical), ABTB1 (11% identical), KLHL11 (10% identical), KBTBD4 (10% identical).
Diseases named in the same sentence as SPOPL in open-access papers:
SPOPL is named in the same sentence as 8 diseases in open-access papers, as found by Europe PMC text mining. Sharing a sentence is not in itself a finding about the gene and the disease. The quoted sentences say what the papers report.
osteosarcoma (2 papers, 2023 to 2025). A usually aggressive malignant bone-forming mesenchymal neoplasm, predominantly affecting adolescents and young adults. "In osteosarcoma, miR-197-3p has been shown to increase cancer stem cellularity and resistance to chemotherapy by inhibiting the SPOPL gene." (PMID 41009512, 2025). "The present study revealed that miR-197-3p significantly downregulated SPOPL expression by binding the promoter of SPOPL, maintaining osteosarcoma stemness and chemoresistance." (PMID 36769824, 2023). "In this study, we found elevated miR-197-3p expression in MTX-resistant osteosarcoma cell lines and targeted SPOPL." (PMID 36769824, 2023). "In summary, the study suggested that miR-197-3p was essential in possessing osteosarcoma stemness and chemotherapy resistance by targeting tumor suppressor SPOPL." (PMID 36769824, 2023). "The results suggested that the miR-197-3p-SPOPL axis was essential to facilitate osteosarcoma chemoresistance and stemness." (PMID 36769824, 2023). "We attempted to uncover the mechanisms of miR-197-3p-SPOPL-mediated osteosarcoma stemness and chemoresistance." (PMID 36769824, 2023). "Collectively, we discovered miR-197-3p conferred osteosarcoma stemness and chemotherapy resistance by targeting SPOPL, prompting promising therapeutic candidates for refractory osteosarcoma treatment." (PMID 36769824, 2023). "The function of SPOPL in osteosarcoma is still poorly understood." (PMID 36769824, 2023).
prostate carcinoma (2 papers, 2020 to 2023). A carcinoma that arises from epithelial cells of the prostate gland. "In here, we unveil a strong association between ZBTB38 and several clinico-pathological and genomic features of prostate cancer, including a strong association with SPOP and SPOPL alterations." (PMID 32365491, 2020). "Interestingly, deletion of CHD1, deletion of SPOPL and mutation of SPOP tend to co-occur in prostate cancer tumours." (PMID 32365491, 2020). "SPOPL deletion is found in The Cancer Genome Atlas prostate cancers, comparable to SPOP deletion in prostate cancer." (PMID 36769824, 2023). "This hypothesis remains to be tested but it grants further investigation of ZBTB38 as a molecular driver of prostate cancer progression, in relation to SPOP/SPOPL functions." (PMID 32365491, 2020).
breast carcinoma (1 paper, 2019). "After survival analysis and ROC curve analysis of each DERNA, eight lncRNAs (AC104472.1, PSORS1C3, DSCR9, OSTN-AS1, AC012074.1, AC005035.1, SIAH2-AS1, and ERVMER61-1) and one mRNA, SPOPL, were identified as prognostic factors in breast cancer." (PMID 31572452, 2019).
metastatic prostate carcinoma (1 paper, 2020). A carcinoma that arises from the prostate gland and has spread to other anatomic sites. "Monitoring ZBTB38 expression level in tumours might thus be useful, in combination with other genetic alterations (i.e., SPOP/SPOPL), to target metastatic prostate cancer with doxorubicin-based therapies." (PMID 32365491, 2020).
prostate tumours (1 paper, 2020). "ZBTB38 mRNA expression, in combination with other genetic alterations (i.e., SPOP/SPOPL), might thus be useful to identify localised prostate tumours that will exhibit more aggressive behaviour and target metastasis with doxorubicin-based therapies." (PMID 32365491, 2020).
tumor (4 papers, 2020 to 2024). "Although much knowledge of SPOP in regulating tumor stemness has been gained, studies of SPOPL in controlling stemness are limited." (PMID 36769824, 2023). "Moreover, we observe a multitude of structural variations (SVs) in these sites, most notably deletions, inversions or tandem duplications at well-described PCa SV loci like tumor suppressors SPOPL at chr2q and DCC/BCL2 at chr18q." (PMID 36450752, 2022). "As for others, CTC, GIGYF1, MTUS2, POM121, PTP14, SPOPL, and ZNF 208 were detected only in tumor tissue, and none were determined to be pathogenic by both algorithms concordantly." (PMID 38254245, 2024).
cancer (2 papers, 2023 to 2025). A tumor composed of atypical neoplastic, often pleomorphic cells that invade other tissues. "Previous research suggested three genes, Speckle-Type BTB/POZ Protein-Like (SPOPL), Mitogen-Activated Protein Kinase 1 (MAPK1), and Bone Morphogenetic Protein Receptor Type 2 (BMPR2) were associated with stemness in cancers." (PMID 36769824, 2023).
SPOPL also shares sentences with these, for which no sentence is quoted: asthma (1 paper).